BRAF (B-Raf proto-oncogene, serine/threonine kinase)
Diseases named in the same sentence as BRAF in open-access papers (continued):
Sharing a sentence is not in itself a finding about the gene and the disease.
glioma (continued). "In addition, circ-BRAF is significantly reduced in glioma patients with a higher pathological grade." (PMID 30064463, 2018). "Importantly, the previous studies of Axl in glioma used tumor cell sources expressing wild-type BRAF." (PMID 27611946, 2017). "Emerging clinical data and our preclinical study argue for a similar mechanism in glioma where BRAF mutation does not always appear to be predictive for responsiveness to BRAF inhibitor therapy." (PMID 27713119, 2016). "In vivo, somatic cell gene transfer of the BRAF-KD did not cause tumors to develop; however, gliomas were detected in 21% of the mice following Ink4a/Arf loss." (PMID 25821557, 2015). "MAPK pathway and BRAF status have been widely explored over the last few years showing that the histologic spectrum of low grade gliomas and glioneuronal tumors is vague but individualizing a group of low grade glioma with MAPK signaling pathway deregulation." (PMID 26671581, 2015). "We show that although the BRAF-KD is not tumorigenic on its own, cooperation with Ink4a/Arf loss leads to the development of relatively indolent but highly atypical and cellular gliomas in vivo." (PMID 25821557, 2015). "A recent study using a glioma model in which there is concomitant BRAF V600E mutation and CDKN2A loss, as seen in our patient, demonstrated that these tumors respond to asingle-agent BRAF inhibitor." (PMID 25563358, 2014). "BRAF V600E mutations are found in small subsets of some low-grade gliomas, including cerebellar and non-cerebellar pilocytic astrocytomas, pleomorphic xanthoastrocytomas and gangliogliomas." (PMID 25563358, 2014). "Murine models of BRAF V600E mutant gliomas suggest that BRAF inhibitors may be active in this setting." (PMID 25563358, 2014). "Additionally, our laboratory is currently seeking to exploit recent findings that suggest crosstalk between the BRAF and PI3K/mTOR signaling pathways as driving mutations in pediatric gliomas." (PMID 23717811, 2013). "The activating BRAF V600E is found in 10–25% of grade 2–4 pediatric gliomas." (PMID 23717811, 2013). "Furthermore, inclusion of additional commonly used and novel emerging markers such as Ki67 tumor cell proliferation index (gliomas), INI1 protein loss (atypical teratoid/rhabdoid tumor) or BRAF V600E mutation status (melanoma brain metastases) seems desirable." (PMID 22720693, 2012). "While BRAF V600E mutations have been described as a common mutation in ganglioglioma (GG) by both our group and others, the frequency of BRAF V600E mutation in other low-grade gliomas has not been investigated in depth." (PMID 21479234, 2011). "PLX‐4720, a BRAF inhibitor, could reduce the growing capacity of glioma cells independent of BRAF mutation status." (PMID 41438616, 2025). "This is the largest cohort reported so far on the effects of MEK and BRAF inhibitors on sodium and glucose homeostasis for a range of indications being represented, thus allowing the frequency of off-target effects of molecular therapies to be estimated in populations other than low-grade gliomas." (PMID 39671021, 2025). "Moreover, this pathway reactivation is consistent with the pattern of RAS reactivation observed in other solid cancers and in BRAF V600E glioma lines upon adaptive resistance, underscoring the significance of RAS-ERK signaling for survival and proliferation in these gliomas." (PMID 40900823, 2025). "Importantly, we show for the first time that monitoring BRAF V600E by ddPCR could serve as treatment response assessment in gliomas." (PMID 39751690, 2025). "Because p-ERK profiling is not yet a Clinical Laboratory Improvement Amendments–approved (CLIA-approved) biomarker that could be analyzed from commercial datasets, we relied on the published literature indicating that MAPK activation is the oncogenic mechanism for BRAF-driven gliomas." (PMID 39137048, 2024).
glioma (continued). "Both pharmacological inhibition of MEK1 / 2, rapid downstream phosphorylation sites of BRAF, and stable silencing of BRAF through lentiviral transduction of shRNA prevented proliferation and stopped the formation of advanced tumor cells derived from low‐grade gliomas." (PMID 37675821, 2023). "Patients with BRAF mutations may benefit from this therapy even if their tumors are not low-grade gliomas." (PMID 37629304, 2023). "Therefore, the co-dependency of KCNMA1 and p-BRAF is highlighted as critical for BRAF-mutated glioma progression and, due to this, KCNMA1 could be a valuable potential therapeutic drug target for the treatment of tumors with BRAF mutations." (PMID 36763212, 2023). "However, only a few novel treatments were introduced, such as BRAF-related targeting therapies in low-grade gliomas, and preliminary studies of histone deacetylase (HDAC) inhibitors in paediatric high-grade gliomas, necessitating the development of new therapeutic strategies." (PMID 37370764, 2023). "Studies have not investigated the range of BRAF mutations, co-occurring alterations, and their clinical implications across a large set of sequenced genes, nor have there been robust comparisons of BRAF alteration types between adult and pediatric gliomas." (PMID 36854806, 2023). "Similarly, Trametinib forms the backbone of several ongoing glioma clinical trials in combination with the BRAF inhibitor, dabrafenib (GSK-2118436), including pediatric patients with newly diagnosed HGG (NCT03919071) and NF1-LGG or LGG with RAS pathway aberrations (NCT03363217)." (PMID 36730269, 2023). "In order to test how chromosome compaction influences the spectrum of BRAF fusion partners seen in JPAs, we generated in situ Hi-C for 8 primary JPA tumors (two with linked-read data available), one primary and relapse tumor from the same patient and one cortical pediatric low-grade glioma." (PMID 36503484, 2022). "Notably, low-grade glioma with BRAF aberrations often arises in the cerebellum." (PMID 36686797, 2022). "cMYC inhibitor may hold promise for the management of tumors caused by MYB and MYBL1 translocations, Downstream MEK inhibitors are already in phase 2 in clinical trials for children with BRAF fused gliomas and phase 1 studies with FGFR1 inhibitors have started recently." (PMID 35574540, 2022). "Therefore, further restricting the FGFR1 sequencing analysis to non-diffusely growing gliomas/MNGT tumors would yield 15% FGFR1 N546/K656 mutant cases after exclusion of cases with BRAF fusion, IDH1/2, NF1 or TERT mutation." (PMID 35018490, 2022). "Besides, mutation of phosphatase and tensin homolog deleted on chromosome ten (PTEN), neurofibromatosis (NF1), isocitrate dehydrogenase (IDH), B-Raf Proto-Oncogene (BRAF), and chromosome 1p19q co-deleted are common in glioma, even being used for molecular classification and prognosis prediction." (PMID 35785151, 2022). "This sample was initially classified as a high-grade glioma based on a Ki-67 of 31% and very frequent mitoses however, the patient is still alive with no signs of recurrence 5 years later, which, in combination with the BRAF fusion, suggests that JPA is in fact the correct diagnosis." (PMID 36503484, 2022). "In pediatric gliomas the MAPK pathway or its downstream effectors, which contribute to tumorigenesis and growth of many types of cancers, can be activated as a consequence of NF1 and BRAF gene mutations In addition, BMP signaling, is also active in pediatric HGG tumor cells." (PMID 33790740, 2021). "However, recent clinical trials have shown that the drug has good efficacy in BRAF V600E mutant malignant astrocytomas and low-grade gliomas; patients with high expression of MMP14 may predict the better curative effect of vemurafenib treatment." (PMID 34712139, 2021).
glioma (continued). "Furthermore, BRAF p.V600E mutation is frequently associated with additional SNVs, including homozygous CDKN2A deletions, that carry the risk of transforming a PLGNT to a higher-grade glioma, specifically in PXAs." (PMID 33779771, 2021). "The results above might imply that the BRAF-mutant clone could not expand to metastasis region, although this mutation contributed to cell proliferation, which consisted with the findings in glioma." (PMID 33014052, 2020). "Next, we tested the impact of BRAF-inhibition on the expression of the respective ETS-factors and found that only ETS1 expression, but not expression of GABPA or the different GABPB splice variants, were significantly and consistently downregulated throughout all BRAFV600E-mutated glioma." (PMID 31391125, 2019). "We strongly recommend limiting the use of RAF/MEK inhibitors to the setting of a clinical trial, but combination therapy may represent a viable treatment option for patients with BRAF V600-mutated recurrent glioma who are not eligible for trial." (PMID 31466300, 2019). "Finally, in a glioma TH03_0290_S01 with a BRAF p.V600E mutation, the mutation was not expressed in the RNA." (PMID 31651965, 2019). "Apart from a single substitution V600E mutation, other mutations in the BRAF gene, which can occur in IDH-wildtype gliomas and glioneuronal tumours, include rearrangements, duplications and fusions with other genes and their detection may be diagnostically helpful." (PMID 29098416, 2018). "In other LEATs, the BRAF mutation has been observed in 30-51% of DNTs and in 3/10 of the recently described polymorphous low-grade neuroepithelial tumours of the young (PLNTY), but not in multinodular and vacuolating neuronal tumours (MVNT) and angiocentric gliomas." (PMID 29963264, 2018). "In addition to H3K27M, genetic aberrations affecting the RAS-MAPK pathway including KIAA1549-BRAF and other BRAF, RAF and FGFR fusion events, as well as BRAF and FGFR1 point mutations have been described primarily in hemispheric low grade gliomas in adults and children." (PMID 27577993, 2016). "Many mutated BRAF proteins exist, but specifically the oncogenic BRAF fusions and BRAFV600E caused by a missense mutation may prove to be the most prevalent and targetable in pediatric glioma." (PMID 26525348, 2015). "Knowing that the BRAF V600E mutations could induce mesenchymal transition in some tumors and that such mutations have been reported in a subset of pediatric glioma, we sequenced exon 15 of the BRAF gene in 20 of the DIPG irrespective of their subgroup." (PMID 22389665, 2012). "While KIAA1549::BRAF remains the most prevalent fusion, an expanding repertoire of alternative fusion partners continues to refine the molecular landscape of MAPK-driven gliomas and has important therapeutic implications." (PMID 41659712, 2026). "In BRAF V600E-mutant HGG, dual BRAF and MEK inhibition affects glioma plasticity, promoting an immunomodulatory phenotype with elevated PD-L1 expression and improving the synergy with ICIs." (PMID 41514664, 2026). "Tovorafenib has recently received approval for treatment of pediatric low-grade gliomas driven by KIAA1549:BRAF, a constitutively dimerized form of BRAF created by its truncation and fusion with a portion of the KIAA1549 ORF." (PMID 41072765, 2025). "Consequently, mitogen-activated protein kinase kinase (MEK) inhibitors (MEKi) and BRAF inhibitors (BRAFi) have been developed, and clinical trials have been designed to assess their efficacy based on a predefined genetic alteration detected in pediatric gliomas." (PMID 41050069, 2025). "Current studies have identified a clear role for targeted therapies in tumors harboring the common molecular alterations, but there are limited options for those with non-BRAF or NF-1-altered tumors, such as FGFR-altered glioma." (PMID 40422539, 2025).
glioma (continued). "For that purpose, we analyzed two more pediatric glioma tissues, one additional PA (ICGC_PA74, KIAA1549::BRAF fusion) and one pleomorphic xanthoastrocytoma (PXA, a CNS WHO grade 2–3 tumor, I007_024, BRAF V600E and CDK2 NA/B deletion)." (PMID 40229354, 2025). "In glioma models, we observed that knockdown of SHP2 prevented adaptive upregulation of ERK activity in response to BRAF or MEK inhibitors." (PMID 40900823, 2025). "BRAF and MEK inhibitors are used to treat a range of paediatric tumours including low-grade gliomas." (PMID 39671021, 2025). "In both HGG murine models (PDGFb and BRAF V600E), myeloid cells were the most abundant immune cell types in the TME, reflecting the immune landscape observed in glioma patients." (PMID 40527978, 2025). "BRAF p.V600E glioma cell lines were tested to evaluate the impact of combined SHP2 and BRAF inhibition on ERK pathway activity, cell growth/death, and tumor forming ability." (PMID 40900823, 2025). "Successful trials of IDH-inhibitors for IDH-mutant astrocytoma, BRAF inhibitors for BRAF-mutant glioma, and MEK inhibitors for pediatric low-grade glioma have demonstrated the potential impact of targeted therapy for gliomas, but unfortunately not yet in GBM." (PMID 39472976, 2024). "These MG-Act cells were enriched in the BRAF fusion PAs compared with ANB and high-grade glioma (HGG) (scRNA data obtained from Gene Expression Omnibus [GEO] GSE249263)." (PMID 39137048, 2024). "Glioma harboring BRAF-V600E were mostly classified as MTC, whereas PG-LGG harboring KIAA1549-BRAF fusion or BRAF wild-type were enriched with GPM and NEU tumors, respectively." (PMID 36732634, 2023). "With recent implementation in clinical use, BRAF and MEK inhibitors are increasingly used in treatment of pediatric and adult patients with glioma." (PMID 37781183, 2023). "Using the Drosophila RafGOF glioma model, together with patient samples and cell lines, we have uncovered the mechanisms of how K+ channels slo/KCNMA1 and p-BRAF strongly enhance glioma growth." (PMID 36763212, 2023). "Using MEK, BRAF and SHP2 inhibitors, he demonstrated the potential therapeutic advantage of combined BRAF and SHP2 inhibition in MEKi-resistant BRAF mutant glioma preclinical models." (PMID 37846765, 2023). "The use of BRAF and MEK inhibition in adult gliomas is also formally being investigated in several larger studies." (PMID 37124503, 2023). "This p-BRAF and KCNMA1 level codependency in mammalian cells was highly reminiscent of that previously observed in Drosophila RafGOF glioma brains." (PMID 36763212, 2023). "Although BRAF mutants are rare in GBM, but more frequent in pediatric gliomas, the MEK/ERK signaling pathway is often activated due to NF1 or upstream receptor kinase mutations." (PMID 37325516, 2023). "Despite these challenges, there are promising data to support the use of BRAF inhibitors alone and in combination with MEK inhibitors for patients with both low-grade and high-grade glioma across age groups." (PMID 37124503, 2023). "In low grade glioma with activation of the MEK/ERK pathway, aberrations in BRAF or NF1 MEK inhibition with trametinib or selumetinib revealed promising activity in pediatric patients." (PMID 36566461, 2023). "None harbored alterations within genes of the MAP kinase signaling pathway (e.g., BRAF, KRAS, NF1, and PTPN11) that are also common in pediatric gliomas." (PMID 36437415, 2023).
glioma (continued). "The next speaker was Dr Abiola Ayanlaja, a post-doctoral research fellow (John Hopkins University, USA), who delivered a presentation on targeting SHP2-dependent adaptive resistance to BRAF and MEK inhibition in glioma." (PMID 37846765, 2023). "Studies in various phases of development are already in progress assessing both BRAF and downstream MEK inhibitors for the treatment of gliomas in children." (PMID 35574540, 2022). "Both lesions were resected revealing an oligodendroglioma WHO grade-2 and a diffuse low-grade glioma, MAPK pathway-altered (BRAF V600E-mutant)." (PMID 36568179, 2022). "Unexpectedly, Sorafenib led to accelerated tumor growth in children with BRAF-fused and NF1-driven low-grade gliomas, most likely due to ERK/MAPK paradoxical activation." (PMID 36698391, 2022). "Clinical trials utilizing dual BRAF and MEK inhibition for newly diagnosed and relapsed patients with V600-mutant gliomas are currently ongoing." (PMID 34965294, 2021). "Agents targeting BRAF inhibit the downstream altered MAPK pathway, which is often altered in solid tumors and is also an important driver of cell proliferation in glioma patients." (PMID 34359651, 2021). "For example, the MEK inhibitor selumetinib demonstrated activity in BRAF V600E-mutant, KIAA1549:BRAF fusion positive and NF1-mutant (lower grade) gliomas, providing a rationale for its evaluation in HGAP." (PMID 33905054, 2021). "Combined inhibition of BRAF and MEK in gliomas was also investigated in the ROAR basket trial; in the group of high-grade gliomas, response rate was 27%, and the disease control rate was 57%." (PMID 34359651, 2021). "This suggests that the assessment of the status of BRAFAMP and IDH1/2 in adult glioma/glioblastoma patients has prognostic value as these patients have relatively short survival times and may benefit from personalized targeted therapy using BRAF and/or MEK inhibitors." (PMID 33489866, 2020). "In our previous study concerning BRAFV600E-positive high-grade glioma, ETS1 was the only ETS factor affected by BRAF inhibition." (PMID 33143299, 2020). "In order to validate the expected dependency of BRAFV600E-mutant glioma on hyperactivated MAPK-signaling, we tested the anti-proliferative effects of the BRAF-inhibitor dabrafenib." (PMID 31391125, 2019). "Three quarters (39/53) of all midline infantile gliomas were RAS/MAPK driven, 97.4% of which (38/39) harbored canonical BRAF alterations." (PMID 31554817, 2019). "The BRAF gene and the TERT promoter are among the most frequently altered genomic loci in low-grade (LGG) and high-grade-glioma (HGG), respectively." (PMID 31391125, 2019). "For instance, BRAF 35, EGFR 36, EZH2 37, MET 38 and mTOR 39 have been reported as potential protein targets for glioma treatment." (PMID 31523189, 2019). "Combination of the BRAF inhibitor dabrafenib and the ETS-factor inhibitor YK-4-279 revealed additive to rather antagonistic effects, especially in the double-mutant glioma cell models." (PMID 31391125, 2019). "The high expression of circ-BRAF is an independent predictive marker for PFS and OS in glioma patients." (PMID 30064463, 2018). "Preliminary results indicated that BRAF inhibitors, such as Dabrafenib or Vemurafenib, are well tolerated in pediatric patients with BRAFV600-positive high-grade gliomas and induce a significant number of patients’ durable objective responses." (PMID 30279357, 2018). "Our observations are consistent with the currently tested combination treatment of BRAF and MEK inhibitors in different BRAF V600E mutant gliomas types, including PXAs60." (PMID 29654229, 2018).